ALG11 (ALG11 alpha-1,2-mannosyltransferase)
Description:
GDP-Man:Man(3)GlcNAc(2)-PP-Dol alpha-1,2-mannosyltransferase that operates in the biosynthetic pathway of dolichol-linked oligosaccharides, the glycan precursors employed in protein asparagine (N)-glycosylation. The assembly of dolichol-linked oligosaccharides begins on the cytosolic side of the endoplasmic reticulum membrane and finishes in its lumen. The sequential addition of sugars to dolichol pyrophosphate produces dolichol-linked oligosaccharides containing fourteen sugars, including two GlcNAcs, nine mannoses and three glucoses. Once assembled, the oligosaccharide is transferred from the lipid to nascent proteins by oligosaccharyltransferases. Catalyzes, on the cytoplasmic face of the endoplasmic reticulum, the addition of the fourth and fifth mannose residues to the dolichol-linked oligosaccharide chain, to produce Man(5)GlcNAc(2)-PP-dolichol core oligosaccharide. Man(5)GlcNAc(2)-PP-dolichol is a substrate for ALG3, the following enzyme in the biosynthetic pathway.
Synonyms: GT8; KIAA0266; CDG1P
Tractability: Antibody: UniProt predicts a signal peptide or a membrane-spanning region. PROTAC: ubiquitination databases record sites on it; its protein half-life has been measured.
Gene: Protein-coding gene on chromosome 13 (52,012,391 to 52,079,232, forward strand). Ensembl gene ENSG00000253710.
Subcellular location: Endoplasmic reticulum membrane
Pathways (Reactome):
Disease: Defective ALG11 causes CDG-1p
Metabolism of proteins: Biosynthesis of the N-glycan precursor (dolichol lipid-linked oligosaccharide, LLO) and transfer to a nascent protein
Gene Ontology:
Molecular function: GDP-Man:Man(3)GlcNAc(2)-PP-Dol alpha-1,2-mannosyltransferase activity; protein binding; alpha-1,2-mannosyltransferase activity; glycosyltransferase activity
Biological process: dolichol-linked oligosaccharide biosynthetic process; protein N-linked glycosylation
Cellular component: endoplasmic reticulum membrane; membrane
Genetic constraint (gnomAD): Loss-of-function variants: 27 observed, 41.01 expected, observed/expected ratio (o/e) 0.66, 90% interval 0.48 to 0.91. The upper end of that interval is the gene's LOEUF score, 0.91, which puts it in group 3 of 6, group 1 being the genes least tolerant of losing a copy. Missense variants: 535 observed, 610.86 expected, observed/expected ratio (o/e) 0.88, 90% interval 0.81 to 0.94. Synonymous variants: 199 observed, 224.87 expected, observed/expected ratio (o/e) 0.88, 90% interval 0.79 to 1.
Gene-disease validity (ClinGen):
ClinGen rates the evidence that ALG11 causes each of these diseases.
ALG11-congenital disorder of glycosylation (autosomal recessive): Moderate. A form of congenital disorders of N-linked glycosylation characterized by facial dysmorphism (microcephaly, high forehead, low posterior hairline, strabismus), hypotonia, failure to thrive, intractable seizures, developmental delay, persistent vomiting and gastric bleeding.
Homologues: Orthologues: macaque ALG11 (99% identical), chimpanzee ALG11 (98% identical), dog ALG11 (90% identical), guinea pig ALG11 (87% identical), rat Alg11 (87% identical), mouse Alg11 (86% identical), rabbit ALG11 (85% identical), pig ALG11 (84% identical), tropical clawed frog alg11 (67% identical), zebrafish alg11 (63% identical), Drosophila melanogaster Alg11 (45% identical), Caenorhabditis elegans algn-11 (41% identical). Paralogues in human: ALG2 (20% identical), PIGA (14% identical), GLT1D1 (13% identical).
Diseases named in the same sentence as ALG11 in open-access papers:
ALG11 is named in the same sentence as 11 diseases in open-access papers, as found by Europe PMC text mining. Sharing a sentence is not in itself a finding about the gene and the disease. The quoted sentences say what the papers report.
chordoma (1 paper, 2014). Chordomas are rare malignant tumors arising from embryonic remnants of the notochord in axial skeleton. "We found ALG11 and PPP2CB to be up- and TMEM144 to be differentially regulated in large physaliferous MUG-Chor1 cells, hence being putative effector genes for chordoma cell development." (PMID 24503940, 2014). "Although only described in the context of glycosylation, we hypothesize that ALG11 could be involved in biosynthesis of glucosaminoglycans/aggrecan that represent a key component of the extracellular matrix of chorda dorsalis, nucleosus pulposus, and classical chordoma." (PMID 24503940, 2014).
gastroesophageal reflux (1 paper, 2022). "Dysphagia and/or gastroesophageal reflux was present in ALG1‐, ALG6‐, ALG11‐, ALG12‐, DPM1‐, and DOLK‐CDG." (PMID 35279850, 2022).
ovarian carcinoma (1 paper, 2022). A malignant neoplasm originating from the surface ovarian epithelium. "To gain insight into changes in mannosyltransferases (ALGs), which have been found (ALG1, ALG2, ALG3, ALG9, ALG11 and ALG12) in ovarian cancer, we queried publicly available transcriptomic data, including Gene Expression Omnibus (GEO, GSE18520) and The Cancer Genome Atlas (TCGA) datasets." (PMID 36231102, 2022).
pneumocystis pneumonia (1 paper, 2024). "Interestingly, the authors also found that drugs used to prevent Malaria and pneumocystis pneumonia (PCP) relapses, such as Primaquine, have therapeutic potential against SARS-CoV-2 based on the interaction of Primaquine with the TIM complex, consisting of TIMM29 and ALG11." (PMID 38166530, 2024).
cancer (1 paper, 2021). A tumor composed of atypical neoplastic, often pleomorphic cells that invade other tissues. "First, we showed that AC displays a glycogene signature characterized by 42 glycogenes, where some of them, such as ALG11, ALG9, and B3GALT5, can be relevant for cancer patients." (PMID 34540372, 2021).
metabolic disease (1 paper, 2014). A congenital disorder (due to inherited enzyme abnormality) or acquired (due to failure of a metabolically important organ) disorder resulting from an abnormal metabolic process. "ALG11 is also known to cause severe human metabolic disease if mutated." (PMID 24503940, 2014).
ALG11 also shares sentences with these, for which no sentence is quoted: epilepsy (2 papers); infection (2); fructose intolerance (1); microcephaly (1); neurodegenerative disease (1).